TRIM14 (tripartite motif containing 14)
Diseases named in the same sentence as TRIM14 in open-access papers (continued):
Sharing a sentence is not in itself a finding about the gene and the disease.
tumor (continued). "Results showed that the expression trend of TRIM14 was identical with hsa_circ_0060927 in OLK and OSCC, and we observed a positive correlation between hsa_circ_0060927 and TRIM14 expression in OLK and OSCC tumor tissues." (PMID 35087744, 2021). "How TRIM14 engages AIF in NSCLC remains unclear, but our results raise the possibility that caspase-independent cell death pathways may partly mediate TRIM14 tumor suppressive function." (PMID 28059079, 2017). "TRIM14 has been shown to interact with Glutamine: Fructose-6-Phosphate Amidotransferase 1 (GFAT1), the rate-limiting enzyme in the hexosamine biosynthesis pathway (HBP), promoting its ubiquitination-mediated degradation, thereby suppressing HBP flux and exerting tumor-suppressive effects." (PMID 41463095, 2025). "Moreover, TRIM14 interacts with GFAT1, a key rate-limiting enzyme in the hexosamine biosynthesis pathway (HBP), and promotes its ubiquitination degradation, thereby inhibiting HBP and playing a tumor-suppressive role." (PMID 39719450, 2024). "In addition, TRIM14 promotes the expression of SPHK1 in CRC cells, which can catalyze the formation of Sphingosine 1-phosphate, thereby inducing constitutive activation of STAT3 and promoting tumor angiogenesis, growth, and metastasis." (PMID 39719450, 2024). "Based on the results showing a tumor-promoting effect of hsa_circ_0060927 on LEUK1 cells, the study next evaluated whether the effects of hsa_circ_0060927 were mediated by the miR-195-5p/TRIM14 axis." (PMID 35087744, 2021).
cancer (25 papers, 2017 to 2025). A tumor composed of atypical neoplastic, often pleomorphic cells that invade other tissues. "In previous studies, TRIM14 was considered as an oncogene in a variety of cancers, and its high expression was associated with cancer cell proliferation, invasion, and poor prognosis of patients." (PMID 35087744, 2021). "Collectively, emerging evidence suggests that aberrant TRIM14 expression is associated with mechanisms regulating a complex interplay between immune response and cancer." (PMID 28059079, 2017). "TRIM14 has been implicated to play an oncogenic role in different cancers." (PMID 34656078, 2021). "It would be interesting to examine whether cells with TRIM14 expression in cancer cells are more susceptible to IFN anti-proliferative effects in immunocompetent animal models." (PMID 28059079, 2017). "Specifically, TRIM14, TRIM25, TRIM32, TRIM44, TRIM59, and TRIM29 exhibit abnormal expression in different cancer types and have been linked to patient prognosis." (PMID 39273003, 2024). "Elevated TRIM14 expression is also involved in the formation of cancer-initiating cells and epithelial-mesenchymal transition, and is strongly associated with resistance to DDP in TSCC." (PMID 39719450, 2024). "At the same time, lncRNA ElNF1-AS1, which is up-regulated due to hypoxia, can positively regulate the expression of TRIM14 through sponging miR-191-5p, thus exerting the cancer-promoting effect of TRIM14." (PMID 39719450, 2024). "For example, TRIM14 is inhibited by miR-15b and enhances cancer-initiating cell phenotypesoral in tongue squamous cell cancer." (PMID 35652045, 2022). "On the contrary, overexpression of some oncogenic TRIMs in various cancers is frequently due to the loss of miR dependent gene suppression (e.g., TRIM11, TRIM14, TRIM24, TRIM25, and TRIM44)." (PMID 33673719, 2021). "TRIM14 was found to be involved in the development of various types of cancers such as gastric cancer, breast cancer, and osteosarcoma." (PMID 34656078, 2021). "Previous studies indicated that TRIM14 played a tumorigenic role in various types of cancer and miR-23b-5p was down-regulated in human mesenchymal stem cell-derived exosomes (HMSC-exos) of AML patients." (PMID 34656078, 2021). "Contrary to this, overexpression of some oncogenic TRIMs in various cancers is frequently due to the loss of miR dependent gene suppression as demonstrated—e.g., for TRIM11, TRIM14, TRIM24, TRIM25, and TRIM44." (PMID 33066016, 2020). "A number of gene nodes linked to drug resistance in other cancer types (including CAT, TRIM59, ANXA2, ADM, AJUBA, HSPA1A/1B, LAMC2, TRIM14, KRT8, KRT18, KRT9, CLDN1, and SMARCA2) were also down-regulated in PARPis-sensitive AsPCs." (PMID 33213473, 2020). "Moreover, circ_0048764 partakes in BC tumorigenesis by sponging miR-1296-5p, similar to circRPPH1, leading to elevation of TRIM14 which is known as a cancer-progression promoting factor whose depletion induces apoptosis and results in better cancer prognosis." (PMID 36380816, 2023). "TRIM14, situated at 9q22.33 and 4480 bp in length, is involved in multiple cell processes—including intracellular signal transduction, growth, and apoptosis—and is related to the pathogenesis of miscellaneous cancers." (PMID 37628777, 2023). "TRIM14 was identified as an oncogene in a variety of cancers." (PMID 33892646, 2021). "In colon cancer, TRIM14 promoted cancer cell invasion by targeting the SPHK1/STAT3 pathway." (PMID 33982666, 2021). "However, the function of miR-195-5p and TRIM14 was still obscured in the process of oral pre-cancer transformation." (PMID 35087744, 2021). "Across human cancer types, TRIM14 aberrations vary from amplifications in one cancer type and deletions in another, alluding to the possibility of tissue- and cell-type specific roles of TRIM14." (PMID 28059079, 2017). "It is evident that TRIM14 may play diametrically opposite roles in different cancers." (PMID 39719450, 2024).
cancer (continued). "Tripartite motif containing 14 (TRIM14), a member of the TRIM protein family, plays a role in several biological processes and is often dysregulated in human cancers." (PMID 40936702, 2025). "This suggested that TRIM14 maintained Dvl2 stability to activate the Wnt/β-catenin signaling pathway, thereby promoting OXA resistance and autophagy in cancer cells, highlighting its potential as a target to overcome drug resistance." (PMID 39768197, 2024). "Activation of the NF-κB pathway is also positively correlated with TRIM52, TRIM14, and TRIM31 and promotes cancer development in cancers." (PMID 36261847, 2022). "In terms of intestinal inflammation and cancer, a direct contribution of autophagy has been demonstrated for TRIM11 and TRIM14." (PMID 33066016, 2020). "Other members of TRIM family proteins, such as TRIM14, TRIM24 and TRIM98 have been reported to enhance chemoresistance in certain human cancers." (PMID 31992359, 2020). "Tripartite Motif Containing 14 (TRIM14) is a member of TRIM family proteins, which are involved in the pathogenesis of various cancers." (PMID 30555277, 2018). "In sum, TRIM14 promotes the PI3K/AKT pathway by reducing PTEN, enhancing cancer cell invasiveness." (PMID 39768197, 2024). "But why TRIM14 does not exist as a cancer-promoting factor, as it does in other cancers, is a question worth pondering." (PMID 39719450, 2024). "Additionally, TRIM66, TRIM52 and TRIM14 also play an oncogenic role in CRC, since they are involved in cancer proliferation and metastasis through the regulation of STAT3 pathway expression." (PMID 33673719, 2021). "Little is known about the role of TRIM14 in normal and disease states and it remains unclear how TRIM14 is downregulated in NSCLC and cancers in general." (PMID 28059079, 2017).
infection (8 papers, 2016 to 2025). The state of being infected such as from the introduction of a foreign agent such as serum, vaccine, antigenic substance or organism. "To then determine if TRIM14 functioned through a transcription-independent mechanism during infection, we compared host mRNA produced during Lm infection (6 hours) in cells expressing TRIM14 or luciferase as a control." (PMID 28002492, 2016). "We found that tripartite motif-containing proteins (TRIMs) including TRIM38, TRIM21, and TRIM14 were significantly enriched during infection with mosquito-borne (West Nile virus strain Kunjin and Zika virus (ZIKV)) and tick-borne (Langat virus (LGTV)) flaviviruses." (PMID 40431659, 2025). "Promoting the expression of TRIM14 may be a strategy to enhance the anti-infection ability of the body." (PMID 39719450, 2024). "IFN I-induced expression of TRIM14 favors the recruitment of USP14, a deubiquitinase which in turn promotes further IFN I expression by modifying and protecting cGAS from autophagy-mediated degradation; thus, Trim14−/− mice are more susceptible to infection." (PMID 30167845, 2018). "Here, we demonstrated that enforced expression of TRIM14 could potently inhibit the infection and replication of HCV in hepatocytes, whereas TRIM14 knockout cells became more susceptible to HCV infection." (PMID 27578425, 2016). "For example, upon infection with the Ebola virus (EBOV), intracellular TRIM14 can interact with EBOV nuclear protein (NP) to promote TRIM14-mediated IFN-β and NF-κB promoter activity to play an anti-EBOV role." (PMID 39719450, 2024). "Consistently, overexpression of TRIM14 restricted the infection of HCV and knockout of TRIM14 enhanced the infection of HCV." (PMID 27578425, 2016). "In the present study, we verified the inhibitory function of TRIM14 to HCV replication and infection on JFH cells and Huh7 cells." (PMID 27578425, 2016). "In addition, we found that TRIM14 significantly inhibited the degradation of Smc5/6 by HBx, and this result was similar to that obtained with the HepG2-NTCP infection system." (PMID 30150992, 2018). "Conversely, the increase in TRIM14 expression (1.5-fold change) suggested an active response to NDV infection, indicating that TRIM14 may play a role in initiating the modulation of the host’s defense mechanisms following infection at 24 hpi." (PMID 39728450, 2024).
adenocarcinoma (2 papers, 2017 to 2019). A common cancer characterized by the presence of malignant glandular cells. "Given that lung squamous carcinoma and adenocarcinomas are often considered two distinct diseases due to different mutation spectrums, we postulate that TRIM14 may behave differently in the two histological subtypes." (PMID 28059079, 2017).
bacterial infections (1 paper, 2023). "Western blot analysis showed changes in TRIM8 and TRIM14 protein expression, confirming the involvement of the proteins in the immune response to the studied bacterial infections." (PMID 37686095, 2023).
TRIM14 also shares sentences with these, for which no sentence is quoted: cervical cancer (2 papers); acute myeloid leukemia (1); Alzheimer disease (1); cardiac insufficiency (1); cardiovascular disease (1); cervical tumors (1); cholangiocarcinoma (1); endometrial cancer (1); Hepatitis (1); hepatitis C virus infection (1); joint diseases (1); measles (1); multiple myeloma (1); neuroblastoma (1); oral cancer (1); osteoarthritis (1); rectal cancer (1); spinal cord injury (1); thyroid carcinoma (1).